HECW1 (HECT, C2 and WW domain containing E3 ubiquitin protein ligase 1)
Description:
E3 ubiquitin-protein ligase that mediates ubiquitination and subsequent degradation of DVL1. Also targets the mutant SOD1 protein involved in familial amyotrophic lateral sclerosis (FALS). Forms cytotoxic aggregates with DVL1, SSR3 and mutant SOD1 that lead to motor neuron death in FALS.
Synonyms: KIAA0322; NEDL1
Tractability: PROTAC: ubiquitination databases record sites on it; its protein half-life has been measured.
Gene: Protein-coding gene on chromosome 7 (43,112,629 to 43,566,001, forward strand). Ensembl gene ENSG00000002746.
Subcellular location: Cytoplasm
Subcellular location (Human Protein Atlas): Nucleoli fibrillar center; Cytosol
Pathways (Reactome):
Signal Transduction: Degradation of DVL
Gene Ontology:
Molecular function: protein binding; ubiquitin protein ligase activity; ubiquitin-protein transferase activity
Biological process: negative regulation of canonical Wnt signaling pathway; regulation of dendrite morphogenesis; ubiquitin-dependent protein catabolic process; protein ubiquitination
Cellular component: cytosol; cytoplasm
Genetic constraint (gnomAD): Loss-of-function variants: 48 observed, 144.47 expected, observed/expected ratio (o/e) 0.33, 90% interval 0.26 to 0.42. The upper end of that interval is the gene's LOEUF score, 0.42, which puts it in group 1 of 6, group 1 being the genes least tolerant of losing a copy. Missense variants: 1,582 observed, 1,951 expected, observed/expected ratio (o/e) 0.81, 90% interval 0.78 to 0.85. Synonymous variants: 789 observed, 789.03 expected, observed/expected ratio (o/e) 1, 90% interval 0.94 to 1.06.
Homologues: Orthologues: macaque HECW1 (99% identical), chimpanzee HECW1 (99% identical), pig HECW1 (92% identical), rabbit HECW1 (90% identical), guinea pig HECW1 (89% identical), mouse Hecw1 (89% identical), rat Hecw1 (88% identical), dog HECW1 (83% identical), tropical clawed frog hecw1 (78% identical), zebrafish hecw1b (68% identical), zebrafish HECW1 (60% identical). Paralogues in human: HECW2 (55% identical), HUWE1 (20% identical), WWP1 (20% identical), NEDD4L (19% identical), NEDD4 (18% identical), ITCH (18% identical), WWP2 (18% identical), SMURF1 (17% identical), SMURF2 (17% identical), HECTD4 (16% identical), HERC2 (15% identical), UBR5 (14% identical), and 12 more.
Diseases named in the same sentence as HECW1 in open-access papers:
HECW1 is named in the same sentence as 27 diseases in open-access papers, as found by Europe PMC text mining. Sharing a sentence is not in itself a finding about the gene and the disease. The quoted sentences say what the papers report.
breast carcinoma (4 papers, 2017 to 2023). "This locus is represented by rs978056 (P = 3.3x10-5), an intronic SNP in HECW1 (encoding E3 ubiquitin ligase) previously studied in the context of colon and breast cancer." (PMID 28187132, 2017). "HECW1, an E3 ubiquitin ligase, is involved in the regulation of non-small cell lung cancer, breast cancer, and thyroid cancer by mediating the ubiquitination and degradation of target proteins." (PMID 38049396, 2023). "Recently, HECW1 protein was found in relatively low levels in neuroblastoma and breast cancer compared with normal tissue." (PMID 31057023, 2019). "Additionally, HECW1 has been found to negatively regulate ErbB4 protein expression via ubiquitin-mediated degradation in breast cancer." (PMID 34348693, 2021).
clear cell renal cell carcinoma (3 papers, 2021 to 2024). "Besides, the low expression of HECW1, a kind of E3 ubiquitin‐protein ligase, has been proved to indicate the poor prognosis of clear cell renal cell carcinoma, suggesting its potential role in future study." (PMID 38403992, 2024). "However, HECW1 was significantly down-regulated in clear cell renal cell carcinoma." (PMID 36362280, 2022).
familial amyotrophic lateral sclerosis (2 papers, 2019 to 2022). An instance of amyotrophic lateral sclerosis that is caused by an inherited modification of the individual's genome. "HECW1 was found to ubiquitinate familial amyotrophic lateral sclerosis (FALS)-linked superoxide dismutase-1 gene for degradation which might contribute to the pathogenesis of FALS." (PMID 31057023, 2019). "The HECW1 protein also ubiquitinates the mutant form of the superoxide dismutase (SOD1) enzyme in people with hereditary amyotrophic lateral sclerosis, binds to amyloid-sensitive epithelial sodium channels and possibly participates in the regulation of their activity." (PMID 36362280, 2022).
non-small cell lung carcinoma (2 papers, 2021 to 2023). A group of at least three distinct histological types of lung cancer, including non-small cell squamous cell carcinoma, adenocarcinoma, and large cell carcinoma. "Exome sequencing studies have revealed somatic mutations in HECW1, along with other novel driver genes, in non-small cell lung cancer (NSCLC)." (PMID 34348693, 2021). "Recently, mutations of HECW1 have been identified in non-small cell lung cancer and muscle-invasive transitional cell carcinoma." (PMID 34348693, 2021). "In contrast, HECW1 promotes the progression of malignant behavior in non-small cell lung cancer by mediating the ubiquitination and degradation of Smad4." (PMID 38049396, 2023). "In addition, the biological function of HECW1 was reported only recently in a paper showing that HECW1 promoted the proliferation, migration and invasion of non-small cell lung cancer cells." (PMID 34348693, 2021).
Alzheimer disease (1 paper, 2022). A progressive, neurodegenerative disease characterized by loss of function and death of nerve cells in several areas of the brain leading to loss of cognitive function such as memory and language. "Previous reports have linked the TEAD1, HECW1, SEMA6A, COL13A1 and LAMA2 genes with different age-related cancers, the PLAT and ACE genes with cardiovascular disease, the ACE and HECW1 genes with Alzheimer’s disease and the SEMA6A gene with type 2 diabetes." (PMID 36362280, 2022).
cervical cancer (1 paper, 2024). A primary or metastatic malignant neoplasm involving the cervix. "Cervical Cancer: HECW1 (HECT, C2, and WW domain-containing E3 ubiquitin protein ligase 1) is an E3 ubiquitin ligase that plays a role in protein ubiquitination and degradation." (PMID 39594618, 2024).
glioma (1 paper, 2023). A benign or malignant brain and spinal cord tumor that arises from glial cells (astrocytes, oligodendrocytes, ependymal cells). "The deficiency of HECW1 accelerates the malignant progression of glioma cells." (PMID 38049396, 2023). "As expected, ferroptosis inducers (erastin, RSL3) significantly inhibited glioma cell growth and accelerated cell death; however, this effect was largely offset by HECW1 silencing." (PMID 38049396, 2023). "To uncover the mechanism by which HECW1 plays a role in cancer inhibition, we treated glioma cells with different cell death inhibitors." (PMID 38049396, 2023). "This decrease in LDH release confirmed that HECW1 knockdown reduced glioma cell death." (PMID 38049396, 2023). "Moreover, overexpression of HECW1 significantly increased glioma cell death, which was largely reversed by Fer-1 treatment." (PMID 38049396, 2023). "Here, we demonstrated the regulatory mechanism of the HECW1/ZNF350/NCOA4 pathway on ferroptosis in gliomas, which might provide a novel strategy for glioma treatment." (PMID 38049396, 2023). "Furthermore, HECW1 knockdown significantly enhanced glioma cell activity." (PMID 38049396, 2023). "HECW1 and ZNF350 are involved in the biological processes of many tumors, but their specific effects and mechanisms on glioma are still unclear." (PMID 38049396, 2023). "More importantly, we explore and demonstrate the role and mechanism of the HECW1/ZNF350/NCOA4 pathway in regulating ferroptosis and identify new molecular targets for glioma therapy." (PMID 38049396, 2023). "Taken together, we confirmed that HECW1, ZNF350, and NCOA4 form an integral pathway involved in the regulation of ferroptosis in gliomas." (PMID 38049396, 2023). "In summary, this study is the first to reveal the influence of HECW1 and ZNF350 on gliomas and their potential value in evaluating patient prognosis." (PMID 38049396, 2023). "In addition, we demonstrated that ZNF350 overexpression reversed the HECW1-induced accumulation of MDA, ROS, and Fe2+ in glioma cells." (PMID 38049396, 2023).
motor neuron diseases (1 paper, 2023). "They highlight a gene of interest in ALS and motor neuron diseases, HECW1, which encodes NEDL1, an E3 ligase that has been poorly studied to date in the central nervous system." (PMID 36674783, 2023).
tumor (7 papers, 2019 to 2025). "The list included the genes MAD1L1, HECW1, and ANKIB1, which have been reported to be involved in mitotic checkpoint control and have been previously implicated in tumor progression." (PMID 40722723, 2025). "Low expression of HECW1 is related to unfavorable prognosis, higher tumor staging, and stronger resistance to targeted drugs in patients with renal clear cell carcinoma." (PMID 38049396, 2023). "Moreover, lower HECW1 expression was found in ccRCC patients with a higher tumor node metastasis (TNM) stage, bone metastasis, or first-line targeted drug resistance (p < 0.001)." (PMID 34348693, 2021). "The results of these previous studies indicate that HECW1 may act as a tumor suppressor gene in cancer." (PMID 31057023, 2019).
cancer (6 papers, 2019 to 2023). A tumor composed of atypical neoplastic, often pleomorphic cells that invade other tissues. "The results revealed that NEDD4L and HECW2 were significantly downregulated while HECW1 was significantly upregulated in cancer tissues compared with normal tissues." (PMID 35090513, 2022). "However, to elucidate the function of HECW1 in other malignant tumors, including ccRCC, additional studies are needed in the future." (PMID 34348693, 2021).
HECW1 also shares sentences with these, for which no sentence is quoted: neuroblastoma (3 papers); amyotrophic lateral sclerosis (1); Angelman syndrome (1); autism (1); cardiovascular disease (1); Cognitive impairment (1); diabetes (1); Ebola (1); epilepsy (1); hydronephrosis (1); IgA nephropathy (1); Intellectual disability (1); lung carcinoma (1); muscular atrophy (1); neurodegenerative disease (1); thyroid cancer (1); type 2 diabetes (1).